BLVRA (biliverdin reductase A)
Description:
Reduces the gamma-methene bridge of the open tetrapyrrole, biliverdin IXalpha, to bilirubin with the concomitant oxidation of a NADH or NADPH cofactor. Does not reduce bilirubin IXbeta. Uses the reactants NADH or NADPH depending on the pH; NADH is used at the acidic pH range (6-6.9) and NADPH at the alkaline range (8.5-8.7). NADPH, however, is the probable reactant in biological systems.
Synonyms: BLVR; BVR; BVRA; BVRalpha
Tractability: Small molecule: a structure with a bound ligand is known; it has a high-quality binding pocket. PROTAC: ubiquitination databases record sites on it; its protein half-life has been measured.
Gene: Protein-coding gene on chromosome 7 (43,758,009 to 43,808,097, forward strand). Ensembl gene ENSG00000106605.
Subcellular location: Cytoplasm, cytosol
Subcellular location (Human Protein Atlas): Cytosol
Pathways (Reactome):
Cellular responses to stimuli: Cytoprotection by HMOX1
Metabolism: Heme degradation
Gene Ontology:
Molecular function: biliberdin reductase (NADH) activity; biliverdin reductase (NADPH) activity; biliverdin reductase [NAD(P)H] activity; protein binding; nucleotide binding; protein serine/threonine kinase activity; RNA polymerase II cis-regulatory region sequence-specific DNA binding; zinc ion binding
Biological process: heme catabolic process
Cellular component: cytosol; extracellular exosome; cell surface; cytoplasm; nucleus
Genetic constraint (gnomAD): Loss-of-function variants: 22 observed, 36.67 expected, observed/expected ratio (o/e) 0.6, 90% interval 0.43 to 0.86. The upper end of that interval is the gene's LOEUF score, 0.86, which puts it in group 3 of 6, group 1 being the genes least tolerant of losing a copy. Missense variants: 323 observed, 377.39 expected, observed/expected ratio (o/e) 0.86, 90% interval 0.78 to 0.94. Synonymous variants: 119 observed, 149.74 expected, observed/expected ratio (o/e) 0.79, 90% interval 0.68 to 0.93.
Gene-disease validity (ClinGen):
ClinGen rates the evidence that BLVRA causes each of these diseases.
hyperbiliverdinemia (autosomal recessive): Moderate. Hyperbiliverdinemia is a rare, genetic hepatic disease characterized by the presence of green coloration of the skin, urine, plasma and other body fluids (ascites, breastmilk) or parts (sclerae) due to increased serum levels of biliverdin in association with biliary obstruction and/or liver failure.
Homologues: Orthologues: macaque BLVRA (99% identical), chimpanzee BLVRA (99% identical), dog BLVRA (94% identical), guinea pig BLVRA (90% identical), rabbit BLVRA (90% identical), pig BLVRA (89% identical), rat Blvra (83% identical), mouse Blvra (82% identical), tropical clawed frog blvra (53% identical), zebrafish blvra (52% identical), Drosophila melanogaster CG17712 (13% identical). Paralogues in human: DHDH (18% identical), GFOD2 (15% identical), GFOD1 (15% identical).
Diseases named in the same sentence as BLVRA in open-access papers:
BLVRA is named in the same sentence as 57 diseases in open-access papers, as found by Europe PMC text mining. Sharing a sentence is not in itself a finding about the gene and the disease. The quoted sentences say what the papers report.
Insulin resistance (13 papers, 2019 to 2025). Increased resistance towards insulin, that is, diminished effectiveness of insulin in reducing blood glucose levels. "Abnormal biliverdin reductase-A (BVR-A) levels were observed in both T2D and AD and were associated with insulin resistance." (PMID 38843768, 2024). "One driving factor in the development of CNS insulin resistance is inhibition of biliverdin reductase-A (BVR-A), an important upstream regulator of the IR signaling pathway." (PMID 35884888, 2022). "Notably, BLVRA is also a member of the insulin receptor substrate family, modulating the glucose uptake, with insulin resistance frequently observed in Alzheimer’s disease." (PMID 32971784, 2020). "More investigations are needed about the regulatory factors that control BLVRA and BLVRB expression and the bilR bacterial enzyme and their functional roles in fatty liver, MASLD, insulin resistance, insulin clearance, and T2DM." (PMID 39873298, 2025). "While biliverdin reductase-A (BVRA) protected against hepatic steatosis via PPARα activation, BVRA knockout mice on a HFD were glucose insensitive and BVRA was lower in obese humans with insulin resistance." (PMID 31577826, 2019).
Hepatic steatosis (8 papers, 2019 to 2022). Steatosis is a term used to denote lipid accumulation within hepatocytes. "Hence, a hepatocyte-specific knockout of biliverdin reductase A (BVRA), the enzyme responsible for producing bilirubin, causes severe hepatic steatosis and glucose intolerance." (PMID 34067839, 2021). "Biliverdin reductase-A (BVR-A) is a substrate of InsR; in obese animal models, the loss of liver BVR-A is related to glucose/insulin changes and fatty liver disease." (PMID 35330934, 2022). "In the present study, we found that liver biliverdin reductase A (BVRA) inhibits the protective effect of glycogen synthase kinase 3 (GSK3β) on hepatic steatosis by enhancing serine 9 phosphorylation." (PMID 33204683, 2020).
Alzheimer disease (7 papers, 2019 to 2025). A progressive, neurodegenerative disease characterized by loss of function and death of nerve cells in several areas of the brain leading to loss of cognitive function such as memory and language. "Similarly, reduced BLVRA levels increased oxidative stress and Tau phosphorylation in young triple transgenic AD (3xTg-AD)mice, suggesting loss of BLVRA impaired neuroprotection in response to oxidative stress in Alzheimer’s disease (AD)." (PMID 32290442, 2020). "Deregulation of the BLVRA activity is a common feature of Alzheimer’s disease, at least in the most advanced stages, with BLVRA inhibition enhancing Tau phosphorylation and deposition in the brain." (PMID 32971784, 2020).
Hyperbilirubinemia (6 papers, 2015 to 2024). An increased amount of bilirubin in the blood. "Further research effort in Indonesia is warranted to investigate other potential genetic factors in different pathways leading to hyperbilirubinemia, including BLVRA and HMOX1." (PMID 31253110, 2019).
Obesity (5 papers, 2020 to 2024). Accumulation of substantial excess body fat. "Other patients had choleliths, but it is unknown if their BLVRA deficiency contributed to their formation because cholelithiasis is common and other risk factors were present (e.g., female gender, pregnancy, and obesity)." (PMID 39766828, 2024).
diabetes (4 papers, 2011 to 2023). "The role of HMOX1 and BLVRA in inflammation associated with diabetes has recently been reviewed." (PMID 32082188, 2020).
Glucose intolerance (2 papers, 2020 to 2021). Glucose intolerance (GI) can be defined as dysglycemia that comprises both prediabetes and diabetes. "Recent investigations have shown that biliverdin reductase-A (BVRA) can bind to the insulin receptor and increase sensitivity for glucose uptake, implicating it may be a potential therapeutic for reversing glucose intolerance." (PMID 32131495, 2020).
hepatocellular carcinoma (2 papers, 2018 to 2022). A malignant tumor that arises from hepatocytes. "BLVRA has been found to be upregulated in both hepatocellular carcinoma and colorectal cancer and is expected to be a prognostic marker and potential therapeutic target." (PMID 35736499, 2022). "In fact, increased BLVRA expression has been observed in patients with hepatocellular cancer and in breast and lung cancer cell lines." (PMID 30057678, 2018). "In fact, the increased expression of BLVRA has been demonstrated in patients with hepatocellular cancer, as well as in breast and lung cancer cell lines." (PMID 30057678, 2018).
ischemia (2 papers, 2015 to 2020). A hypoperfusion of the BLOOD through an organ or tissue caused by a PATHOLOGIC CONSTRICTION or obstruction of its BLOOD VESSELS, or an absence of BLOOD CIRCULATION. "Here, we examined the effect of Tat-BLVRA against oxidative stress-induced hippocampal neuronal cell death and in an insult animal model of ischemia." (PMID 32290442, 2020). "Based on our results, Tat-BLVRA protected hippocampal neuronal cell death from oxidative stress, suggesting that BLVRA may provide a novel therapeutic agent for ischemia." (PMID 32290442, 2020). "In this study, the effects of transducible fusion protein Tat-BLVRA on H2O2-induced HT-22 cell death and in an animal ischemia model were investigated." (PMID 32290442, 2020).
liver cancer (2 papers, 2021 to 2024). An epithelial or non-epithelial malignant neoplasm that arises from the liver. "Additionally, heme degradation enzymes displayed an interesting contrasting pattern of isozyme BLVRA and BLVRB gene expression, indicating that normal hepatocytes and liver cancer lines utilize different processes for heme degradation." (PMID 39199347, 2024).
nuclear cataract (2 papers, 2022). A cataract (disease) that involves the lens nucleus. "The results revealed that the mRNA expressions of Nrf2, HO-1, and biliverdin reductase A (BVRA) were all decreased in human samples of age-related nuclear cataract." (PMID 35480872, 2022).
anemia (1 paper, 2024). A reduction in the number of red blood cells, the amount of hemoglobin, and/or the volume of packed red blood cells. "Anemia and hemolysis are not features of BLVRA knockout mice and were also not described in the few human patients with BLVRA deficiency." (PMID 39766828, 2024).
childhood asthma (1 paper, 2025). "Strong evidence of colocalization was observed between BLVRA and childhood asthma, categorizing it as a tier 1 target (PPH4 = 0.567)." (PMID 41398767, 2025).
esophageal cancer (1 paper, 2022). A primary or metastatic malignant neoplasm involving the esophagus. "BLVRA expression has been shown to be elevated in many cancers, including liver, lung, breast, skin, and esophageal cancers." (PMID 35736499, 2022).
hemorrhagic disease (1 paper, 2021). Spontaneous or near spontaneous bleeding caused by a defect in clotting mechanisms (blood coagulation disorders) or another abnormality causing a structural flaw in the blood vessels (hemostatic disorders). "Most of these genes are known to be involved in the manifestation of various clinical phenotypes, such as metabolic diseases (CPT1B and BLVRA); hemorrhagic diseases (RUNX1 and GP6); and neuronal disorders (KCNAB3, FAM179B, CCDC60, GRM6, and PRDM8), among others." (PMID 34440289, 2021).
hyperbiliverdinemia (1 paper, 2024). "A complicating factor in determining inheritance of BLVRA deficiency is that it appears to have incomplete penetrance for hyperbiliverdinemia in the absence of cholestatic disease." (PMID 39766828, 2024).
liver diseases (1 paper, 2023). "Besides, SOX17, SULT2A1, and BLVRA have potential roles to play in other liver diseases." (PMID 36777627, 2023).
liver fibrosis (1 paper, 2024). "In this perspective, the increased salivary expression of biliverdin reductase A in patients with PSC could be indicative of its cytoprotective activity against liver fibrosis." (PMID 39683940, 2024).
pancreatic cancer (1 paper, 2018). "Nevertheless, in our in vitro studies on human pancreatic cancer cells, we did not observe any effects of chlorophylls on BLVRA expression." (PMID 30057678, 2018).
prostate carcinoma (1 paper, 2023). A carcinoma that arises from epithelial cells of the prostate gland. "Overexpression of BLVRA protein had been detected in prostate cancer tissue as a diagnostic biomarker by MALDI-MS." (PMID 37501157, 2023).
cancer (11 papers, 2015 to 2024). A tumor composed of atypical neoplastic, often pleomorphic cells that invade other tissues. "The siRNA oligos for GLUL, ALDH2, BLVRA or FBP1 were introduced into cancer tissue derived CA-13 cells." (PMID 38580938, 2024). "Subsequent GSEA also suggested that differential BLVRA expression in patients with TETs was enriched in cancer pathways as well as pathways such as the phosphatidylinositol signaling system." (PMID 35736499, 2022). "For details relevant to BLVRA in human physiology, the reader should refer to excellent previously published reviews focusing on BLVRA in cytoprotection, metabolism, inflammation, and cancer." (PMID 37237924, 2023). "Overexpression of BLVRA has been reported in many diseases, including cancer." (PMID 35736499, 2022). "Therefore, biliverdin reductase A peptides as inhibitors could be considered in combination with CA to prevent the cancer cells from using this pathway to become resistant." (PMID 37174677, 2023). "SCNV gain was identified in several genes such as E2F1, ASPH, BLVRA, and CEBPB across multiple cancers." (PMID 37497116, 2023).
cardiovascular diseases (3 papers, 2019 to 2024). "Our primary focus is on their roles in cardiovascular diseases, the result uncovered involvement of ADK, BLVRA, ALDH1B1, UGDH, and HIBCH." (PMID 39369254, 2024).
tumor (3 papers, 2015 to 2022). "Enrichment analysis of the global protein expression data across all tumor samples showed that the heme degradation pathway enzymes BLVRA and HMOX2, as well as the mitogenic kinase RPS6KA1, among others, are significantly upregulated in EGFRm samples." (PMID 35360705, 2022).
BLVRA also shares sentences with these, for which no sentence is quoted: metabolic disease (5 papers); breast carcinoma (3); neuroblastoma (3); Acute hepatitis (2); kidney diseases (2); metabolic syndrome (2); atherosclerosis (1); Autoimmunity (1); cataract (1); cholelithiasis (1); cholestasis (1); chronic kidney disease (1); colorectal cancer (1); Crigler-Najjar syndrome (1); dementia (1); Down syndrome (1); endometriosis (1); glioblastoma (1); hemolysis (1); hemorrhage (1); kidney tumors (1); lung carcinoma (1); mild cognitive impairment (1); neurodegenerative disease (1); non-small cell lung carcinoma (1); ovarian carcinoma (1); pneumothorax (1); renal carcinoma (1); skin cancer (1); steatosis (1).
A further 4 diseases each share a sentence with BLVRA in 1 paper.